FGFR1 (fibroblast growth factor receptor 1)
Diseases named in the same sentence as FGFR1 in open-access papers (continued):
Sharing a sentence is not in itself a finding about the gene and the disease.
ischemia (5 papers, 2014 to 2025). A hypoperfusion of the BLOOD through an organ or tissue caused by a PATHOLOGIC CONSTRICTION or obstruction of its BLOOD VESSELS, or an absence of BLOOD CIRCULATION. "The FGFR1 protein is involved in maintaining the blood-brain barrier during ischemia and can stimulate angiogenesis and revascularization of the affected area." (PMID 41226594, 2025). "Further studies have found that the intervention of exogenous FGF21 significantly improved the survival of cardiomyocytes under ischemia and decreased the areas of myocardial infarction, whereas it inhibited the expression of FGFR1 increased the infarct area of ischemic myocardium." (PMID 34777697, 2021). "By contrast, transient activation of FGFR1 signaling in cardiomyocytes just prior to the onset of ischemia did not affect outcomes after cardiac I/R injury at 1 day and 7 days after reperfusion." (PMID 36211556, 2022).
myelodysplastic syndrome (5 papers, 2018 to 2025). A clonal hematopoietic disorder characterized by dysplasia and ineffective hematopoiesis in one or more of the hematopoietic cell lines. "For example, chromosomal translocations involving NUP358 gene with FGFR1 lead to myelodysplastic syndrome/myeloproliferative neoplasms (MDS/MPNs), while NUP358 fusions with ALK are associated with acute myeloid leukemia." (PMID 38838144, 2024). "Myeloproliferative neoplasms (MPNs) are a major subgroup of chronic myeloid neoplasms, alongside myelodysplastic syndromes (MDS), MDS/MPN overlap syndromes, and myeloid/lymphoid neoplasms, with eosinophilia associated with recurrent PDGFRA, PDGFRB, FGFR1, or PCM1-JAK2 rearrangements." (PMID 40650198, 2025). "Rearrangements involving the fibroblast growth factor receptor 1 (FGFR1) gene result in 8p11 myeloproliferative syndrome (EMS), which is a rare and aggressive hematological malignancy that is often initially diagnosed as myelodysplastic syndrome (MDS)." (PMID 35081975, 2022).
myocardial infarction (5 papers, 2013 to 2025). Gross necrosis of the myocardium, as a result of interruption of the blood supply to the area, as in coronary thrombosis. "In terms of individual siRNA treatment, administration of a FGFR1, PI3K p110, or Akt1 siRNA caused significant intensification of myocardial infarction." (PMID 24067542, 2013). "FGF21 through the mediation of the FGFR1/β-Klotho–PI3K–Akt1–BAD signaling network to reduce cell death, and myocardial infarction thereby ameliorating myocardial function." (PMID 38789571, 2024). "Based on this, another study in a mice model with myocardial infarction (MI) investigated that 6-week aerobic exercise (10 m/min, 55 min/day, 5 days/week) elevated the protein expression of FGF21 and FGFR1 in cardiomyocytes, as well as decreased oxidative stress and apoptosis." (PMID 40003929, 2025).
neuroendocrine tumors (5 papers, 2014 to 2025). "Sulfatinib is a multi-target kinase inhibitor for treating neuroendocrine tumors, selectively targeting FGFR1/CSF-1R." (PMID 38172256, 2024). "Sulfatinib is a multi-target angio-immuno kinase inhibitor for treating neuroendocrine tumors, selectively targeting FGFR1 and CSF-1R." (PMID 38172256, 2024). "Surufatinib, approved in China in late 2020 for the treatment of well-differentiated extrapancreatic neuroendocrine tumors (NETs), selectively inhibits VEGFR 1, 2, and 3, FGFR1, and CSF-1R, offering a targeted approach to managing these tumors." (PMID 40149728, 2025). "Surufatinib, an oral inhibitor of VEGFR1-3, FGFR1 and CSF1R, has shown durable activity in neuroendocrine tumors." (PMID 41275311, 2025). "All metastases in TRAMP/Fgfr1 null mice were primarily those that escape Fgfr1 disruption and highly expressed FGFR1, or neuroendocrine tumors regardless of FGFR1 status." (PMID 30761180, 2019).
prostate tumor (5 papers, 2016 to 2025). "Mechanistically, the KLF5 acetylation–dependent barrier induced by PTEN deficiency constrained prostate tumor growth by attenuating FGF receptor 1 (FGFR1) signaling." (PMID 38781024, 2024). "In Pten-deficient prostate tumors with Klf5KR mutant, overactivation of Fgfr1 signaling was further supported by increased Fgf9 secretion and upregulated Cx3cr1 expression." (PMID 38781024, 2024). "These GSEA data clearly indicate that interruption of Klf5 acetylation at K358 further enhanced FGFR1 signaling in Pten-deficient prostate tumors." (PMID 38781024, 2024). "Finally, this fgfr1KO escape phenotype has greatly limited our ability to investigate the detailed molecular mechanisms underlying FGFR1 driving prostate tumor metastasis in this model." (PMID 27376150, 2016). "Lastly, it was shown that reported that FGFR1 was upregulated in clinical prostate tumor samples, and treatment with tyrosine kinase inhibitors (TKIs) showed promising antitumor effects depending on FGFR1 expression." (PMID 33456711, 2021). "Nevertheless, prostate tumors exhibit aberrant expression of FGFR1 in epithelial carcinoma cells, and increased expression of FGFR1 seemed to be associated with aggressive tumors." (PMID 31316912, 2019). "This fgfr1KO escape phenotype indicates an essential role of FGFR1 in prostate tumor metastasis." (PMID 27376150, 2016). "We have demonstrated the prognostic features of FGFR1, FRS2, S6K1, LDHB, MYPT1, and P-LDHA in prostate tumors using tissue microarrays (TMAs) which consist of 241 patient samples from Massachusetts General Hospital (MGH)." (PMID 31316912, 2019).
renal fibrosis (5 papers, 2015 to 2026). A final common manifestation of a wide variety of chronic kidney diseases characterized by glomerulosclerosis and tubulointerstitial fibrosis. "This study aims to investigate the role of fibroblast growth factor receptor 1 (FGFR1) as an upstream regulator of YAP1 in renal fibrosis and to evaluate the therapeutic potential of targeting this signaling axis." (PMID 42051262, 2026). "Previous studies have shown that various signaling pathways, including TGF-β, Wnt, the Glucocorticoid receptor, Fibroblast Growth Factor Receptor 1 (FGFR1), and SIRT3, influence renal fibrosis by regulating EndMT." (PMID 38169402, 2024). "Since EMT also contributes to maladaptive repair and parenchymal damage during renal fibrosis, we became encouraged to explore the role of NCAM/FGFR1 signaling as initiating or driving forces of EMT program in cultured human proximal tubular epithelial cells (TECs)." (PMID 30383875, 2018).
squamous non-small cell lung cancer (5 papers, 2014 to 2024). "Fibroblast Growth Factor Receptors (FGFR1–4) have a critical role in the progression of several human cancers, including Squamous Non-Small-Cell Lung Cancer (SQCLC)." (PMID 30972293, 2019). "NCI-H1703 is a squamous non-small cell lung cancer (NSCLC) cell line that harbors both FGFR1 and PDGFRA amplifications." (PMID 27223434, 2016). "A Phase II clinical trial evaluating Dovitinib in advanced squamous non-small cell lung cancer (NSCLC) patients with FGFR1 amplification did not observe a clear correlation between FGFR1 amplification levels and partial response (PR) rates." (PMID 39590377, 2024).
viral infection (5 papers, 2015 to 2026). "Specifically, FGFR1 inhibition enhances the interferon (IFN) response to viral infection, whereas blocking neddylation reduces levels of TMPRSS2 (transmembrane protease serine 2), which is needed for the cleavage of SARS-CoV-2 spike protein to initiate infection." (PMID 41585476, 2026).
Anxiety (4 papers, 2016 to 2025). Intense feelings of nervousness, tension, or panic often arise in response to interpersonal stresses. "As well as seeing altered expression in Fgf1 and Fgfr1, we also see a 46 % decrease in Fgfbp3, a gene that has been associated with the regulation of anxiety." (PMID 27295951, 2016). "While the anxiety index remained unchanged, optogenetic activation of FGFR1 in the dentate gyrus for 12 h per day over 1 week—sufficient to fully activate the FGFR1–Notch–BDNF axis—resulted in a significant increase in sucrose preference and reduction in total immobility time." (PMID 40813470, 2025). "Our findings may shed light on the participation of FGF2/FGFR1 signaling in determining anxiety and mood, where a neuronal role for FGFR1 has been hypothesized (Turner, Watson & Akil, 2012a)." (PMID 28439461, 2017). "Similar to WT mice, corticosterone administration did not alter the anxiety index or locomotor function in region-specific FGFR1-cKO mice compared with the control group." (PMID 40813470, 2025). "With no discernible changes in anxiety level and locomotor function, immobility time was significantly reduced in FGFR1-activated mice with Numb knockdown, compared with both FGFR1-inactive mice with Numb knockdown and FGFR1-activated mice without Numb knockdown." (PMID 40813470, 2025). "Strikingly, these FGFR1 conditional knockout (cKO) mice exhibited depressive-like behaviors after just 1 week of corticosterone administration, without any discernible changes in anxiety index or locomotor function." (PMID 40813470, 2025). "Exogenous FGF2 reduces stress-induced changes in astrocytes which may be a pathway to regulation of anxiety-like behavior; however, anti-anxiety-like effects of FGF2 in mice do not require FGFR1 or R2." (PMID 36906620, 2023).
bladder tumor (4 papers, 2012 to 2025). "For example, alternative splicing of FGFR1 was found to be associated with tumor stage and grade; isoform switch of FGFR1 may result in a proliferative advantage that plays a key role during bladder tumor progression." (PMID 24564989, 2013). "Overall these studies demonstrate that FGFR1, via overexpression or altered splicing, may play a key role during bladder tumour development and/or progression." (PMID 22899908, 2012). "This suggests that the timing and cellular context of FGFR1 dysregulation may be crucial in determining its phenotypic consequences and may influence the development of either superficial or invasive bladder tumours." (PMID 22899908, 2012).
Ewing sarcoma (4 papers, 2005 to 2024). A small round cell tumor that lacks morphologic, immunohistochemical, and electron microscopic evidence of neuroectodermal differentiation. "The Western blot results, therefore, confirm and extend previous studies by detection of FGFR1, -2 and -3 on the protein level in a high percentage of Ewing tumour cell lines." (PMID 15685229, 2005). "In order to identify the receptor(s) that transduces the inhibitory FGF2 signal in Ewing tumour cells, Western blot analyses identified FGFR1, -2 protein in all cell lines, whereas FGFR-3 protein was only detected in TC-71, VH-64 and WE-68." (PMID 15685229, 2005). "FGFR1 has been recently demonstrated to be active in Ewing sarcoma." (PMID 26802024, 2016).
gastric adenocarcinoma (4 papers, 2015 to 2021). "However, minimal activities were achieved against tumours harbouring actionable aberration(s) in FGFR1‐3, including FGFR1‐amplified SqCLC and gastric adenocarcinoma with FGFR2 polysomy or gene amplification." (PMID 33655556, 2021). "Compared with FGFR1 non-amplified gastric adenocarcinoma, FGFR1-amplified cases are associated with poor 10-year survival (p = 0.047) and a higher rate of distant metastasis (p = 0.025)." (PMID 33041789, 2020).
hypertrophic cardiomyopathy (4 papers, 2013 to 2022). A condition in which the myocardium is hypertrophied without an obvious cause. "Acute exercise also induced enrichment in gene sets related to actin/tubulin folding, which cross-talks to many hypertrophic signaling pathways (i.e., MAPK/FGFR1/2) linked to dilated and hypertrophic cardiomyopathy, as well as IQGAPs, PAKs, and AMPK activation (see section “Discussion”)." (PMID 33424629, 2020).
Infertility (4 papers, 2017 to 2022). "Our female patient was successfully treated for her infertility, but because of the autosomal dominant mode of inheritance of FGFR1 mutations, there remains a 50% chance of passing on the gene defect to her offspring." (PMID 35457241, 2022). "Our RNA profiling data strongly support the theory that in the high infertility risk group of cryptorchid boys insufficient PROK2/CHD7/FGFR1/SPRY4 gene expression, together with observed deficient EGR4 and PITX1 signaling, induce deficient LH secretion, which results in impaired mini-puberty." (PMID 29163975, 2017).
inflammatory myofibroblastic tumor (4 papers, 2022 to 2024). A multinodular intermediate fibroblastic neoplasm that arises from soft tissue or viscera, in children and young adults. "LRRFIP1 has been implicated in 8p11 myeloproliferative syndrome through its fusion with FGFR1, in inflammatory myofibroblastic tumors with ALK and in atypical Spitz tumors with MET." (PMID 38338888, 2024).
influenza (4 papers, 2015 to 2023). An acute viral infection of the respiratory tract, occurring in isolated cases, in epidemics, or in pandemics; it is caused by serologically different strains of viruses (influenzaviruses) designated A, B, and C, has a 3-day incubation period, and usually lasts for 3 to 10 days. "Next, the effect of influenza infection in A549 cells on FGFR1 phosphorylation for the indicated times was investigated." (PMID 25909503, 2015). "FGFR1 was shown to significantly impact cellular internalization of two influenza A viruses but FGFR3 was not expressed in the cell line tested, leaving open the possibility of its potential role in the influenza life cycle." (PMID 27403523, 2016). "Notch4 and Fgfr1 represent only two of several putative candidates that may regulate lung endothelial apoptosis and proliferation after H1N1 infection, and the role of these and other pathways in the EC response to influenza merit further evaluation in future studies." (PMID 37233732, 2023).
large cell carcinoma (4 papers, 2011 to 2019). A malignant epithelial neoplasm composed of large, atypical cells. "The anti-tumor activity of UPR1371-UPR1376 was then evaluated in the NSCLC large cell carcinoma H1581 cell line, a cell model that harbors focal amplification of FGFR1 and is exquisitely sensitive to FGFR1 inhibition." (PMID 30972293, 2019). "Furthermore, an elevated level of phosphorylation of the FGFR1 substrate FRS2 was observed in NCI-H1581 large cell carcinoma cells carrying focal amplification of FGFR1, but not in cells harboring relatively broader levels of FGFR1 amplification." (PMID 21666749, 2011).
laryngeal squamous cell carcinoma (4 papers, 2018 to 2025). A squamous cell carcinoma that arises from the larynx. "While the precise mechanism by which Fgfr2 deficiency affects Fgfr1 and Fgfr4 mRNA expression remains unclear, a positive correlation between FGFR1 and FGFR2 expression has been documented in human laryngeal squamous cell carcinoma tissues." (PMID 41151533, 2025). "However, FGFR1 amplification is not prognostic in laryngeal squamous cell carcinomas." (PMID 29351293, 2018).
malignant glioma (4 papers, 2019 to 2025). A grade III or grade IV glioma arising from the central nervous system. "Functionally, FGFR1 expression in malignant glioma has been associated with increased migration of cancer cells." (PMID 31337028, 2019). "Taken together, FGFR1 serves as a critical modulator of malignant glioma pathology, orchestrating major functions that encompass accelerated growth, enhanced invasion, diminished sensitivity to treatment, and stem-like capability." (PMID 41567627, 2025). "In summary, FGFR1 is a key regulator of tumor growth, invasion, therapy resistance, and cancer stemness in malignant glioma." (PMID 31337028, 2019). "In addition, highly expressed in malignant gliomas, EphA4 forms a complex with fibroblast growth factor receptor 1 (FGFR1), accelerating the canonical FGFR1 signalling pathway and resulting in increased cell proliferation and migration." (PMID 33430066, 2021). "In addition to the increased expression of FGFR1 in malignant gliomas, the ratio of alternatively spliced FGFR1 α/β isoforms changes with progression to more aggressive brain cancers." (PMID 31337028, 2019). "A trial of BGJ398 in malignant glioma patients with FGFR1–TACC1 or FGFR3–TACC3 fusion, and/or activating mutation in FGFR1, -2, or -3, was completed, but so far, no results have been published." (PMID 31337028, 2019).
metastatic carcinoma (4 papers, 2012 to 2021). A carcinoma which has spread from the original site of growth to another anatomic site. "Overall, we found Foretinib and Ponatinib to be effective in most of metastatic cancer cell lines compared to primary tumour cell lines, suggesting therapies to target FGFR1 in metastatic cancer." (PMID 33299129, 2021).
Muenke syndrome (4 papers, 2019 to 2025). Muenke syndrome is a syndromic craniosynostosis with significant phenotypic variability, usually characterized by coronal synostosis, midfacial retrusion, strabismus, hearing loss and developmental delay. "Specific missense substitutions in this linker region in FGFR1, FGFR2, and FGFR3 cause Pfeiffer, Apert, and Muenke syndromes, respectively." (PMID 40259859, 2025).
pancreatic adenocarcinoma (4 papers, 2011 to 2022). "In addition, FGFR1 mRNA was found downregulated in human pancreatic adenocarcinoma and we observed a significant downregulation in the mouse PDAC model relative to normal tissues." (PMID 21738581, 2011). "Other cancers with amplification of FGFR1 genes include FGFR1 in pancreatic adenocarcinoma (PDAC), likely expressing the FGFR1-IgIIIc isoform, with FGFR1 amplification in ovarian and urothelial cancer." (PMID 34068954, 2021).
pituitary adenomas (4 papers, 2008 to 2020). "FGFR1 is found in the normal human pituitary as well as in pituitary adenomas, and its mRNA was described in the rat neural and anterior lobe." (PMID 25505910, 2014). "In pituitary adenomas, higher expression of FGF2 and FGFR-1 has been demonstrated in comparison with normal pituitary, with significantly more enhanced expression of FGFR-1 in invasive tumors." (PMID 32012988, 2020). "The overexpression of fibroblast growth factor receptor 1 (FGFR1), a receptor of FGF-2, is also closely related to the invasiveness of pituitary adenomas." (PMID 30733705, 2019). "For example, VEGF, FGF-2, FGFR1, and PTTG, which give a particular vascular phenotype, are modified in human and experimental pituitary adenomas of different histotypes." (PMID 25505910, 2014).
prostate adenocarcinoma (4 papers, 2010 to 2025). "Fibroblast growth factor receptor 1 (FGFR1) is a known EMT inducer whose activation can lead to irreversible prostate adenocarcinoma and EMT." (PMID 21108828, 2010).